CDK1 (cyclin dependent kinase 1)
Diseases named in the same sentence as CDK1 in open-access papers (continued):
Sharing a sentence is not in itself a finding about the gene and the disease.
infection (52 papers, 2008 to 2026). The state of being infected such as from the introduction of a foreign agent such as serum, vaccine, antigenic substance or organism. "A kinase whose activity was significantly regulated only after infection with the capsule-deficient mutant is CDK1." (PMID 37065199, 2023). "Somewhat more intriguing is the effect of CDK1-specific inhibition on BKPyV infection; RO-3306 caused significant reductions in viral DNA synthesis and infectious virus assembly." (PMID 31142673, 2019). "At early times during MVM infection, prior to the loss of cyclin B1, we have shown that the complex was inactive due to the inhibitory phosphorylation of CDK1 (lanes 1 and 2), thus, we expected that at these times cyclin B1 would remain cytoplasmic." (PMID 24415942, 2014). "During the infection caused by Human B19V, the phosphorylation of CDC25C inhibits the activation of CDK1, thereby resulting in the formation of an inactive B1-CDK1 complex." (PMID 40862157, 2025). "The upregulation of CDK1 mediates the activation of Wnt/β-Catenin to promote cell proliferation and counteract infection-induced cell death." (PMID 40996975, 2025). "Following infection with bacterial colibactin, CDK-1 gene expression in Caco-2 cells was found to be downregulated compared to uninfected cells." (PMID 41009865, 2025). "The results of qRT-PCR analysis showed that compared to the mock-infected cells, the transcription levels of Cyclin B and CDK1 were significantly downregulated in Se301 cells and G1 phase P8-Se301-C1 cells 48 h after SeMNPV infection (p < 0.05)." (PMID 38793618, 2024). "The expression of Cyclin B and CDK1 was significantly down-regulated at 48 h post-infection (p < 0.05)." (PMID 38793618, 2024). "The results showed that infection of G1-phase P8-Se301-C1 cells with SeMNPV inhibited Cyclin B and CDK1 expression, as did infection of Se301 cells." (PMID 38793618, 2024). "The prevalence of up-regulated kinase genes highlights a prominent activation of intracellular signaling processes in late-stage infection (Aurka, Aurkb, Cdk1, Tk1, Plk1, Pbk, and Melk) in this article." (PMID 38107402, 2023). "The activity of CDK1 was elevated throughout the infection, which prevents mitotic exit, resulting in MC." (PMID 35412344, 2022). "The model of G2/M checkpoint activation was supported by infection-induced nuclear accumulation of cyclin B1 and Cdk1." (PMID 36568985, 2022). "Quantitative analyses of Cdk1 distribution confirmed the infection-induced significant nuclear accumulation of Cdk1 at late infection." (PMID 36568985, 2022). "Genes involved in cell division, such as cyclin-dependent kinase 1 (cdk1) and cyclin B, were also DR in P. dicentrarchi during infection." (PMID 33076342, 2020). "In our study, the expression of cyclin-dependent kinase inhibitor 1B (CDN1B), cyclin-dependent kinase 6 (CDK6) and cyclin-dependent kinase 1 isoform 1 (CDK1) was found to be downregulated during aMPV/C infection in Vero cells." (PMID 32231136, 2020). "To verify this prediction, we tested the CDK1/CDK2 inhibitor BMS-265246 for its ability to restrict HIV-1ΔEnv-GFP/VSVG infection." (PMID 29764952, 2018). "The expression of CDK2 and cyclinE1 was decreased after 12 h post-infection, and the expression of cyclinB1 and CDK1 was decreased by CVA6 infection at all time point tested (last six rows)." (PMID 30159255, 2018). "As described, MVM uses a very different approach to prevent the activation of the cyclin B1/CDK1 complex: infection inhibits the production of Ccnb1 RNA which leads to the loss of cyclin B1 protein." (PMID 29088070, 2017). "Surprisingly, however, during MVM infection, although activity of the cyclin B1/CDK1 complex is lost, the inhibitory phosphorylation of CDK1 at Tyr-15 is absent-typically an indicator associated with activity of the cyclin B1/CDK1 complex." (PMID 29088070, 2017). "To test this, we examined CDK1/2 expression knowing that CDK1/2 phosphorylates SAMHD1 to deactivate its capacity to restrict infection." (PMID 28122869, 2017).
infection (continued). "CDK1 was decreased at the mRNA level upon EV-D68 infection (transition fromP < 0.01), but cyclinB1 mRNA expression was not significantly regulated." (PMID 28229049, 2017). "At 24 h post MVM infection, CDK1 Y15 inhibitory phosphorylation was significant and comparable to what was observed following doxorubicin treatment (compare lanes 1 and 3)." (PMID 24415942, 2014). "In order to determine the mechanism of G2-arrest following MVM infection, we first examined the activity and phosphorylation status of CDK1 over the course of infection." (PMID 24415942, 2014). "While the Y15 phosphorylation of CDK1 that normally inhibits entry into mitosis was lost as infection progressed, the MVM induced DDR resulted in the near-complete depletion of cyclin B1, thus directly inhibiting cyclin B1-CDK1 complex function." (PMID 24415942, 2014). "Using a chemical inhibitor of CDK1, purvalanol A, we found that CDK1 activity is required for efficient infection by HPVs." (PMID 19247434, 2009). "RT-PCR analysis performed 24 hours post infection with an adenovirus vector expressing DN-NF-YA (Ad-DN-NF-YA) shows that cyclin A2, B2, cdk1, cdc25C, topoisomerase IIα mRNAs were greatly down-regulated (lane 3)." (PMID 18431504, 2008). "We investigated whether CDK1 inhibition disrupts immediate-early (IE) gene expression and analyzed the host phosphoproteome early in infection to identify putative host factors and mechanisms that facilitate HSV-1 IE gene expression and are controlled by CDK1." (PMID 41827841, 2026). "During infection, Cyclin B–Cdk1 contributes to capsid egress by disrupting nuclear lamina, and we previously hypothesized that increased p21 and reduced Cdk1 levels might alter levels of phosphorylated lamin A/C." (PMID 39655950, 2025). "Cluster 1 was more heterogenous and lacked a distinct transcriptional profile, whereas Type I IFN (Isg15, Ifi206, Ifit3, Ccl5) and proliferative signatures (Cdk1, Mki67, Tuba1b) were observed in clusters 3 and 5, respectively, whose numbers remained stable between days 7 and 14 after infection." (PMID 39989461, 2025). "Of note, in G1/S-arrested cells, vDNA remained Golgi-associated after infection at least until 72h p.i., suggesting that it served as efficient ‘waiting room’ for HPV until cell cycle progression into mitosis and, thus, CDK1- and PLK1-mediated phosphorylations of L2 would occur." (PMID 36683055, 2023). "Together, our results suggest that Cdk1- and caspase 3 -mediated mitotic and apoptotic pathways may affect NE permeability in infection, and thereby most likely influence the nuclear egress of progeny capsids." (PMID 36568985, 2022). "CDK1 activity increased in ZIKV infected hiNPC cells from the time of infection." (PMID 35412344, 2022). "The strong correlation between Cdk1 inhibition and a decrease in the cytoplasmic amounts of capsid label is consistent with our results above showing that G2/M checkpoint-mediated NE leakage is required for the nuclear egress of capsids in late infection." (PMID 36568985, 2022). "Of the tissues evaluated in the present study, gene expression in the HRT was the most severely impacted by infection, with significant decreases in all three cell cycle promoters (CDK1, CDK2 and CDK4) and the largest increase in expression of their inhibitor CDKN1A." (PMID 35189966, 2022). "Furthermore, the expression of cyclinB1 and CDK1 was down-regulated after EV-D68 infection, which is consistent with the ability of EV-D68 to promoting the transition from G2/M to G0/G1." (PMID 28229049, 2017). "CDK1 kinase assays using histone H1 as a substrate demonstrated that at both early (24 h pi) and late (32 h pi) time points following MVM infection, CDK1 activity was reduced, to levels seen following control doxorubicin treatment which blocks cells in G2 (compare lanes 1 and 2 with lane 3)." (PMID 24415942, 2014).
infection (continued). "To gain insight into specific host proteins potentially regulated by ERK1/2 and/or CDK1/2 activity during infection, we performed high-confidence group-based phosphorylation scoring (GPS) analyses to define infection-specific phosphopeptides that contain ERK1/2 and CDK1/2 motifs." (PMID 24068923, 2013). "Hence, a relative decrease in abundance within infected cells corresponds to CDK1/2 activation during infection, which was previously documented during productive MHV68 infection." (PMID 24068923, 2013). "To examine whether entry into early prophase is critical for HPV infection, we tested hpvSEAP infection in 293T cells treated with the CDK1 inhibitor, purvalanol A." (PMID 19247434, 2009). "For example, CCNA2 and CDK1 are key regulators of cell cycle progression, and their repression may lead to cell cycle arrest, thereby reducing the proliferation of infected cells and limiting the spread of the infection." (PMID 41000417, 2025). "Importantly, the kinase activity of the cyclin B1/CDK1 complex in MVM infected cells is significantly reduced, suggesting that the loss of this activity plays a key role in maintaining the pre-mitotic cell cycle block during MVM infection." (PMID 29088070, 2017). "triangularis infection-related proteins, highlighting hub genes such as AKT1, TNF, MMP9, CDK1, and PIK3C3, and enriched pathways in autophagy, immune regulation, oxidative stress responses, and kinase-mediated signaling." (PMID 41993607, 2026). "Fluorescence intensity measurements at three days post-infection (dpi) showed that the knockout of DHFR, CDK1, and Cables1 inhibited RCAS(J)GFP infection." (PMID 39307305, 2024). "NN1172-infection leads to the down-regulation of many genes related to cell cycle and DNA replication genes, including MCM 2 ~ 6, CDK1 ~ 2, CCNB2, ANAPC2, MAD2L1, WEE1, RBL1, RB1." (PMID 38362295, 2024). "In support of this mechanism, a previous study reported that infection of Jurkat T cells with arrest-proficient HIV-1 resulted in constitutive phosphorylation of Tyr15 on CDK1, and subsequent inhibition of CDK1-CyclinB nuclear translocation." (PMID 33510734, 2020). "Especially, they found that the dynamic pattern of cell cycle genes such as CDK1, AURKA, and PLK1 are upregulated in early infection (4 hpi), and this upregulation tends to peak at 24 hpi and then precipitously decrease." (PMID 33060827, 2020). "To probe the reversibility of regulation of CDK1/2 and SAMHD1 in MDM, we changed serum 3 days before infection from unstimulating HS to stimulating FCS, and vice versa." (PMID 28122869, 2017). "While NR-1ΔmiR-UL148D infection resulted in sustained inhibition of CDC25B, HCMV IE1 expression was suppressed when the constitutively activated CDK1 mutant was overexpressed in host cells." (PMID 27824944, 2016). "Of note, detection of phosphorylated CDK1 and CDK2 was reduced during infection compared to control samples." (PMID 24068923, 2013). "Notably, a reduction of 40%, 36%, and 44% in RCAS(J)GFP infection rates was observed in DHFR, CDK1, and Cables1 knockout lines, respectively, compared to that in WT DF-1 cells." (PMID 39307305, 2024). "Similarly, flow cytometry results demonstrated that at three dpi with an MOI of 0.01, the infection rates of RCAS(J)GFP were 22%, 23%, 20%, and 35% in DHFR, CDK1, and Cables1 knockout, and WT DF-1 cells, respectively." (PMID 39307305, 2024). "In ZIKV-infected cells however, there was a cytoplasmic accumulation of CDK1 starting at 3 h after infection, independent of any mitotic changes in nuclear morphology." (PMID 35412344, 2022). "CDK1 and CycA accumulated in the cytoplasm of ZIKV-infected cells adjacent to ZIKV RF and all ZIKV-infected cells were positive for cytoplasmic CycA at 24 h after infection." (PMID 35412344, 2022). "Under conditions which permit both WT and NS1′-def viruses to replicate similarly, no obvious alteration of the CDK1 expression was detected upon infection with WT or NS1′-def viruses." (PMID 34756071, 2021).
infection (continued). "The CDK1 activity inhibitor RO3306 or the negative-control DMSO was injected via intravenous route into mice at 3 days after infection with the WT virus." (PMID 34756071, 2021). "Of the top 10 transcripts upregulated at peak HIV-1 viral load, the majority (6 out of 10) were related to cell cycle and cell division including RRM2, MYBL2, CDK1, UBE2C, CDC45, and TK1 with 8 to 15-fold increased expression compared to the pre-infection samples." (PMID 31937782, 2020). "A CDK1 inhibitor was also found to block HPV infection in a dose-dependent manner, suggesting that phosphorylation of NE components by CDK1 and NE breakdown during early prophase is important for HPV nuclear entry and ultimately infection." (PMID 26029198, 2015). "Our proteomics data showed that during early infection, CHIKV affected the expression of proteins that are involved in mRNA processing, host metabolic machinery, UPP, and cyclin-dependent kinase 1 (CDK1) regulation (in favour of virus survival, replication and transmission)." (PMID 23593481, 2013). "In conclusion, our proteomics data suggested that during early infection, CHIKV affects the expression of proteins involved in mRNA processing, host metabolic machinery, UPP, and cyclin-dependent kinase 1 (CDK1) regulation (in favour of virus survival, replication and transmission)." (PMID 23593481, 2013). "Furthermore, seven genes (CDK1, TYMS, MCM5, KIF11, CCNB2, MAD2L1, and MCM4) have been identified as core hub genes involved in cell-cycle regulation, potentially serving as mediators in the pathogenesis triggered by NN1172 infection within the thymus." (PMID 38362295, 2024). "However, the transcription levels of Cyclin B and CDK1 did not change significantly after infection of unsynchronized, S-phase, or G2/M phase P8-Se301-C1 cells." (PMID 38793618, 2024). "Similarly, the infection of human herpesviruses is known to induce cell cycle arrest by enhancing the CDK1 phosphorylation either through perturbing the activities of Wee1 and CDC25C phosphatase or through inactivating the cyclin B-CDK1 complex." (PMID 34756071, 2021). "By simulating infection of the human herpesvirus, cytomegalovirus, we hypothesize that virus-mediated disruption of APC/C is necessary to establish a unique mitotic collapse with sustained CDK1 activity, consistent with known mechanisms of virus egress." (PMID 32251461, 2020). "The interactions of NS1′ with CDK1 were further examined by coimmunoprecipitation (co-IP) assay, and the results showed that during infection with the WT virus, but not with the NS1′-def virus, CDK1 was coprecipitated with NS1′ protein." (PMID 34756071, 2021).
adenocarcinoma (8 papers, 2013 to 2025). A common cancer characterized by the presence of malignant glandular cells. "In regards to 11 kinases specifically regulated in AD, siRNA‐mediated gene‐silencing of CDK1, EPHA1, JAK3, RET and ZAP70 caused loss of cell viability in a panel of six human adenocarcinoma cell lines." (PMID 39995112, 2025). "In the present work, we demonstrate that the chimaera reduces expression of CDK1 protein, opening a new possible therapeutic scenario for KRAS-mutated adenocarcinoma." (PMID 32948832, 2021). "Changes in SERPINE1, CDK1, ZWINT, and FN1 expression were validated using qRT-PCR after HMGB1 silencing or overexpression in PC-3 and LNCaP (selected as an adenocarcinoma model of PCa responding to hormonal treatment) cell lines." (PMID 38542079, 2024). "Of these, survival was best predicted by CDK1 (p<1E-16), CD24 (p<1E-16) and CADM1 (p = 7E-12) in adenocarcinomas and by CCNE1 (p = 2.3E-09) and VEGF (p = 3.3E-10) in all NSCLC patients." (PMID 24367507, 2013). "Consequently, the gene silencing and/or drug‐dependent inhibition of the MR kinases AKT1, CDK1&2, ERBB2 and the downstream kinase EGFR markedly reduced cell viability in a large panel of human adenocarcinoma cell lines." (PMID 39995112, 2025).
hematologic malignancies (7 papers, 2010 to 2024). "CDK1 is a central regulator involved in cell division processes and has been reported to be involved in hematological malignancies." (PMID 39830374, 2024). "Various inhibitors of CDK1, have been developed, and some have entered phase I and II clinical trials for the treatment of a variety of solid tumors and hematologic malignancies." (PMID 31926109, 2020). "In this section we will discuss selected pan CDK inhibitors that also target CDK1 and are used in clinical trials in hematologic malignancies." (PMID 25914884, 2015). "A clinical trial with terameprocol (EM-1421), a novel survivin and cdc2 (CDK1) inhibitor, was done in patients with advanced hematological malignancies." (PMID 20416083, 2010). "Various inhibitors of CDK1, including flavopiridol, BMI-1026, olomoucine, staurosporine, and RO-3306 have been developed, and some have entered phase I and II clinical trials for the treatment of a variety of solid tumors and hematologic malignancies." (PMID 28434945, 2017). "Both CDK1 and WEE-1 inhibitors are currently being used in clinical trials for the treatment of hematologic malignancies (below)." (PMID 25914884, 2015).
neurodegenerative disease (4 papers, 2022 to 2026). A disorder of the central nervous system characterized by gradual and progressive loss of neural tissue and neurologic function. "Similar to other neurodegenerative diseases, this indicated that CDK1 re-expression also happens in RP." (PMID 35883586, 2022). "Moreover, Cdk1 has also been shown to play a critical role in neuronal death and has been reported to contribute to the pathogenesis of neurodegenerative diseases." (PMID 35485294, 2022). "In summary, it is intriguing to find an additional non-mitotic role for Cdk1 in the context of microglial stimulation and it will be valuable to determine the effect of Cdk1 inhibition in in vivo neurodegenerative disease models." (PMID 37813836, 2023).
cardiovascular disease (3 papers, 2022 to 2024). "CDK1 is a protein associated with cardiovascular disease and is involved in the proliferation and differentiation of cardiomyocytes." (PMID 38542439, 2024). "Several previous studies have demonstrated that CDK1 is crucial in both cardiac biological processes and the pathology of cardiovascular diseases." (PMID 35906548, 2022).
neurological disorders (3 papers, 2018 to 2024). "However, roscovitine can also inhibit Cdk1, Cdk2, Cdk7, and Cdk9, the low selectivity for Cdk5 reduces its potential as a drug candidate targeting neurological disorders." (PMID 36438186, 2022). "Interestingly, synergistic neuroprotective effect of Cdk1 and Cdk5 inhibition may be extended to other neuropathological conditions, as both enzymes are individually recognized to contribute to cell death in several neurologic diseases." (PMID 29581894, 2018). "We focused on CDK5 and CDK1 because these two CDKs, unlike other CDKs, are involved in neurological disorders." (PMID 39596381, 2024).
brain disease (1 paper, 2010). "Ser172 of β tubulin is an important residue that is mutated in a human brain disease and phosphorylated by the cyclin-dependent kinase Cdk1 in mammalian cells." (PMID 21042413, 2010).
digestive system cancer (1 paper, 2025). A primary or metastatic malignant neoplasm involving any part of the digestive system. "CDK1 and STAT1 may serve as early diagnostic indicators for kidney injury in patients with digestive system cancers." (PMID 39911265, 2025).
kidney disease (1 paper, 2024). "Finally, a recent study identified the cell cycle regulator CDK1 as a key promoter of early cystogenesis in ADPKD, and crucially demonstrated that genetic ablation of this gene inhibited cell cycle progression and ameliorated kidney disease phenotypes in vivo." (PMID 38846086, 2024).